STAT6 (signal transducer and activator of transcription 6)
Diseases named in the same sentence as STAT6 in open-access papers (continued):
Sharing a sentence is not in itself a finding about the gene and the disease.
cancer (continued). "IL-4 was able to stimulate phosphorylation of STAT6 at significantly lower doses than IL-13 in the human epithelial carcinoma cell line A549, suggesting that STAT6 may not be the main downstream molecular target of IL-13." (PMID 35578342, 2022). "However, we found that murine HGF is not completely inactive on human airway epithelial cells or cancer cell lines but stimulates the phosphorylation of GRB2-associated-binding protein 2 (GAB2) and signal transducer and activator of transcription 6 (STAT6)." (PMID 29771943, 2018). "However, the data also showed a slight, statistically not significant decrease of both STAT6 mRNA and protein levels in cancer-derived primary cells compared to benign cells." (PMID 28553931, 2017). "Notably, after knocking down STAT6 in macrophages, the expression of CD206 stimulated by IL-4 was not reduced by 23-HBA, and 23-HBA failed to inhibit the activation of the IL-10/STAT3/Bcl-2 signaling pathway induced by M2 macrophages and the resulting resistance to 5-FU in cancer cells." (PMID 38554148, 2024). "Although in this study it could not be ruled out that STAT6-dependent effects other than PD-L2 upregulation also played a role, these results indicate that we may in fact already be targeting PD-L2 in cancer patients with one of the clinically most widely used groups of chemotherapeutics." (PMID 22611421, 2012). "This nonhereditary cancer is the result of an environmental intrachromosomal gene fusion between NAB2 and STAT6 on chromosome 12, which fuses the activation domain of STAT6 with the repression domain of NAB2." (PMID 37370737, 2023). "This nonhereditary cancer is the result of an environmental intrachromosomal gene fusion between NAB2 and STAT6 on chromosome 12." (PMID 37370737, 2023). "While our concept targets activated STAT6, PROTAC, as designed for STAT3 in cancer, for instance, does not differentiate between active vs. inactive transcription factors." (PMID 36348405, 2022).
infection (106 papers, 2008 to 2026). The state of being infected such as from the introduction of a foreign agent such as serum, vaccine, antigenic substance or organism. "The weight loss has been directly linked to IL-4 mediated events since treating animals with IL-4c had the same effect as an Hb infection and the weight loss, and increased mortality, was reversed in STAT6 knock out animals." (PMID 38950025, 2024). "The induction of mucus secretion associated to mild infection by Pneumocystis has been described as part of a STAT6/FoxA2 pathway immune response, leading to the increment of the levels of the two most relevant mucins of the airways: Muc5ac and Muc5b." (PMID 37108906, 2023). "For instance, genetic variants in IL13, IL4, IL10, IFNG and STAT6 genes were associated not only with infection intensities and re-infection of S. mansoni after treatment, but also with S. haematobium infections and its infection intensities." (PMID 36889485, 2023). "Measurement of individually isolated fecund adult females at day 7 post-infection revealed that the STAT6-deficient environment also resulted in significantly longer worms." (PMID 38079450, 2023). "Susceptibility to T. crassiceps infection is STAT6-mediated, whereas resistance to this infection is STAT4-dependent." (PMID 34684235, 2021). "Analysis of the mixed population of PEC by qPCR detected increased transcription of STAT-3 and in the later stage of infection also STAT-6, which are associated with anti-inflammatory processes." (PMID 33461599, 2021). "STAT6 has also been associated with the expansion of alternatively activated macrophages (M2 macrophages) in the chronic stage of this infection, leading to the immunosuppression of Th1 responses." (PMID 34684235, 2021). "The notion that IFN-γ and STAT6 deficiency correlate with resistance to infection led us to investigate the role of CAMs and AAMs in the immune response and susceptibility to T. crassiceps." (PMID 23484125, 2013). "This work reveals that loss of STAT6-driven immune responses increases hookworm size and reproductive output and significantly alters the transcriptional profile of these parasites as early as day 5 post-infection." (PMID 38079450, 2023). "In the additive and recessive models, the allele C of SNP rs3024974 located on STAT6 gene was associated with an increased risk of bearing high worm burden or high infection intensities (Z = 2.61, P = 0.009 for additive model; Z = 2.55, P = 0.01 for the recessive model)." (PMID 36889485, 2023). "Interesting mechanistic studies in this system have shown that protection required established infection, as STAT6-deficient mice both cleared the parasite and developed severe colitis; moreover, protection by infection was abolished by anti-IL-10 blocking antibodies." (PMID 28302598, 2017). "Moreover, the number of IL-5- and IL-13-producing CD4 T cells was significantly (p<0.01) reduced in FI-RSV-immunized STAT6-deficient mice at day 7 post-infection." (PMID 25769044, 2015). "Thus, it is unlikely that specific STAT6 genotypes predispose individuals to infection with HCV or contribute to the process of spontaneous viral elimination." (PMID 23651608, 2013). "Furthermore, both studies found that STAT6 was involved during early phase of infection in rendering them more susceptible to cysticercosis and trichinellosis, respectively." (PMID 23509764, 2013). "Conversely, STAT6−/− mice develop a Th1 like response and control infections caused by intracellular protozoan parasites such as Leishmania mexicana and Trypanosoma cruzi indicating that STAT6-mediated signaling pathway inhibits development of protective immunity by inhibiting a Th1 development." (PMID 23509764, 2013). "In conclusion, M1‐and M2‐like signals synergistically regulate Calhm6 expression via Irf1 and Stat6, maintaining a balance between anti‐infection and immune tolerance signals in vivo and preventing macrophages from overly differentiating to either phenotype." (PMID 40999918, 2026).
infection (continued). "Multiple STAT family members were activated during E. chaffeensis infection, including STAT1, STAT3, STAT5, and STAT6; however, using a specific STAT3 inhibitor, most of STAT-related gene expression during infection was found to be associated with STAT3." (PMID 41115066, 2025). "By using PNCs derived from mice deficient in STAT6 (STAT6KO) and infection of STAT6KO mice with wild-type type III parasites (WTIII), we identified that efficient encystment required STAT6 in vitro and in vivo." (PMID 37068104, 2023). "We also found that the parental (WT rat-maintained) stock of N. brasiliensis dramatically altered its transcriptional profile upon exposure to STAT6 KO hosts (G1 infection)." (PMID 38079450, 2023). "Curiously, however, over the course of eight experiments we found that infection of WT mice with STAT6 KO-adapted worms led to a significant increase in host mortality." (PMID 38079450, 2023). "We found an increase in 24-hour egg release of worms at day 7 post-infection in STAT6 KO-adapted worms relative to WT control worms." (PMID 38079450, 2023). "We also performed single-worm mRNA-seq on the two adapted lines, derived from passage hosts at G15 (WT) and G14 (STAT6 KO), isolating adult females at day 7 post-infection." (PMID 38079450, 2023). "To quantify the effects of both specific inhibitors (STAT-6-inhibition and anti IL-10) on intracellular pathogen survival, we quantified intracellular bacteria after 24 h of infection." (PMID 37637102, 2023). "To confirm the reproducibility of the STAT6 encystment defect, we repeated the infection of STAT6KO Cre reporter and control Cre reporter mice for the 3 wpi time point." (PMID 37068104, 2023). "The total number of MLN cells was significantly increased in the STAT6 KO infection condition, suggesting a stronger elicited immune response." (PMID 38079450, 2023). "IL-10 expression was significantly increased in cells infected with KP compared to uninfected cells, and treatment with the STAT-6 inhibitor during infection significantly diminished IL-10 expression in KP infected cells." (PMID 37637102, 2023). "To test this, we sequenced transcripts of individual adult female worms from each cohort (generation 9 for previous WT-adaptation, or generation 7 for previous STAT6 KO-adaptation) after infection in a WT host." (PMID 38079450, 2023). "We therefore measured ATP within worm homogenates (10 worms per measurement) and found significantly increased ATP concentration in STAT6 KO-adapted and derived worms relative to WT controls at day 7 post-infection." (PMID 38079450, 2023). "Contrary to expectation, we found that STAT6 KO-adapted worms had an egg-shedding pattern similar to WT-adapted worms from days 5–8 post-infection, which was confirmed ex vivo." (PMID 38079450, 2023). "Activated in this way, STAT6 regulates a specific set of genes needed to recruit different immune cells to the site of infection." (PMID 35327350, 2022). "The fluorescence images of lung tissues indicated the infection efficiency in both lenti-Veh and lenti-mouse STAT6 groups." (PMID 35668064, 2022). "A recent study on host response to PEDV infection in IPEC-J2 revealed the high expression of the STAT family except STAT5B and STAT6 after infection." (PMID 36733428, 2022). "The transcription levels of various signaling molecules, including IKKβ, p38, STAT1, STAT3, and STAT6, showed a sharp increase from day 6 after infection in HVEM−/− mice, compared with the rapid decrease at the same time in WT C57BL/6 mice." (PMID 35632787, 2022). "When ECAR and OCR analysis following infection were done in the presence of the STAT6 inhibitor AS1517499, we observed a reduction in both measurements (EBI BioStudies accession number S‐BSST892), connecting Klebsiella‐induced metabolism with STAT6 activation." (PMID 36337046, 2022).
infection (continued). "In contrast, there was a significant reduction or failure in activation of type 2-related chemokines/cytokines (Cxcl12, Ccrl1, Il4, Il23a) and signature markers (Stat3, Stat5b, Stat6, Mrc1, Ahr) during infection." (PMID 34320039, 2021). "In two of the groups of animals, one with blocked IL-4Rα and one with rIL-13Rα2 treatment prior to infection, a significant reduction in STAT6 phosphorylation and translocation was observed at 2 wppi compared with the to rIL-25-treated control animals." (PMID 33276813, 2020). "Blocking of IL-4Rα in mice treated with rIL-25 induced a decline in STAT6 phosphorylation and a Th1 response to infection." (PMID 33276813, 2020). "Surprisingly, however, the infection with Mtb per se promoted the LBs accumulation in M(IL-4) macrophages despite the activation of the IL-4/STAT6 axis." (PMID 33002063, 2020). "On the other hand, M2 macrophage-related genes (PPARγ, TGF-β, STAT3, IL5 and STAT6) were significantly up regulated after 24 h of infection." (PMID 30918280, 2019). "The phosphorylation of STAT6 approximately increased by 7- and 6-folds after 6 and 10 weeks of infection with S. japonicum, respectively, compared to the age-matched uninfected group." (PMID 31886304, 2019). "The data herein, can be interpreted in favor of iNOS contributing to the resistance of STAT6−/− mice to infection with L2 T." (PMID 31810203, 2019). "In agreement with the observation that RTA presents in the early stage of primary infection, we also saw the increased expression of STAT6 along with reduced RTA expression in HUVEC cells with KSHV primary infection at longer time points." (PMID 30532138, 2018). "Since KSHV also undergoes lytic replication in the early stages of primary infection, we examined the protein level of STAT6 in human umbilical vein endothelial cells (HUVECs) with de novo infection of KSHV at different time points." (PMID 30532138, 2018). "In this study, we found that T reg cells were actively phosphorylating STAT6 during infection and that IL-4R signaling was required for the conversion of T reg cells to Th2 cells in vitro and in vivo." (PMID 28507062, 2017). "We compared IL-12p40-/- BALB/c mice with IL-12p40-/- STAT6-/- BALB/c mice in a model of intranasal infection by 2x107 CFU of mCherry-Br." (PMID 26376185, 2015). "The most dramatic effects of infection with ECTV-IFN-γbpΔ in the GKO mouse strains were evident in STAT-6−/− and IL-13−/− mice." (PMID 25751266, 2015). "Infection of STAT6 chimeras showed that when STAT6 was limited to bone marrow cells, mice supported larval growth." (PMID 26720604, 2015). "As an example, infection of STAT-6−/− mice with ECTV-WT resulted in increased GzB+ cell numbers over and above those in WT mice and infection with the mutant virus further increased numbers." (PMID 25751266, 2015). "The infection-induced increase in GLUT1 mRNA expression was attenuated in infected STAT6−/− mice, indicating that the infection-induced increase in GLUT1 mRNA is dependent on the STAT6 pathway and immune regulation." (PMID 24465430, 2014). "We showed previously that the nematode-infection inhibition of sodium-linked glucose transport through SGLT1 was STAT6-dependent, so we next determined the STAT6-dependence of infection-induced changes in GLUT1 and GLUT2 expression." (PMID 24465430, 2014). "The treatment of STAT6 KO mice, which develop CAMs and are highly resistant to infection, with an iNOS inhibitor in vivo rendered these mice susceptible to T. crassiceps infection." (PMID 23484125, 2013). "VV-HA-IL-4 infection studies showed that IL-4 and STAT6 was required to up-regulate IL-4Rα expression on naïve and effector CD8+ T cells." (PMID 23383283, 2013). "For example, STAT6−/− mice fail to mount a significant Th2 response and cannot control worm burdens following infection with gastrointestinal helminth parasites." (PMID 23509764, 2013).
infection (continued). "The critical importance of the parasite-induced STAT6-arg1 pathway in infected cells was demonstrated by finding enhanced control of infection following either STAT6 or arg1 knockdown." (PMID 22275864, 2012). "To dissect the role of STAT6 in L. donovani-induced arg1 expression we used the in vitro infection model of the BHK hamster fibroblast cell line." (PMID 22275864, 2012). "Previous studies have demonstrated that direct infection of macrophages by T. gondii tachyzoites can induce arginase expression via STAT-6 dependent and independent pathways." (PMID 23209401, 2012). "The expression of phosphorylated STAT6 was increased in the spleen tissue of hamsters over the course of in vivo infection with L. donovani." (PMID 22275864, 2012). "Knockdown of host arginase or STAT6 enhanced control of the infection, indicating that this activation pathway has a critical role in the pathogenesis of the disease." (PMID 22275864, 2012). "An example is ROP16 that manipulates the host cell transcription factors STAT3 and STAT6 in the early infection." (PMID 21592384, 2011). "It is possible that functional cooperation between IL-4Rα/STAT6 and additional pathways promotes maximal Arg1 expression in alveolar macrophages after infection with A. fumigatus." (PMID 21246055, 2011). "Recently, it has been shown that cytokine-dependent, STAT 6-dependent pathways as well as TLR-dependent, STAT-6 independent pathways can induce arginase-1 in macrophages depending on the type of infection." (PMID 19696894, 2009). "However, infection with Hb and N. brasiliensis reduces glucose absorption by the small intestine in a STAT6 dependent manner." (PMID 38950025, 2024). "Importantly, Stat6 phosphorylation as well as Dclk1 induction were severely impaired in intestines from TgAtf4IEC mice 7 days post-infection, suggesting that tuft cell amplification was abolished upon Atf4 overexpression in vivo." (PMID 39085648, 2024). "Moreover, hookworms had distinct transcriptional profiles in hosts lacking STAT6-driven immune responses, which were apparent as early as day 5 post-infection, and by day 7 show a bias towards overall suppression of gene expression in STAT6 KO hosts." (PMID 38079450, 2023). "Amelioration of altered airway responses after secondary infection could also be achieved with administration of an IL-13Rα2 fusion protein, blockade of IgE, blockade of IL-33 signaling, or inhibition of STAT6 during the primary infection." (PMID 35493465, 2022). "To test whether STAT6 suppression results in ROS accumulation during infection, we infected our knockdown cell lines with WTIII parasites and quantified host cell ROS levels." (PMID 33653884, 2021). "There was a trend toward decreased infection-induced PGD2 in Stat6−/− mice." (PMID 34283207, 2021). "In summary, our work extends awareness of the role(s) of the STAT1 and STAT6 pathways in lung healing during acute T. canis infection and highlights the importance of M2 macrophages in accelerating tissue recovery during the lung stage of this infection." (PMID 31810203, 2019). "Finally, we present evidence demonstrating that K. pneumoniae skews macrophage polarization following infection in a STAT6-dependent manner." (PMID 31796543, 2019). "STAT6 phosphorylation, a marker of IL-13 pathway activation, also began to increase in HSCs, peaking at the same time point, and the production of collagen in HSCs was dramatically elevated at day 42 post-infection." (PMID 29554131, 2018). "In the present study, we have investigated the combined effect of the absence of the Th1-associated IL-12p40 and of the Th2-associated STAT6 proteins on the immunopathology and neutrophil phenotype generated during L. major IR75 infection in the susceptible BALB/c mice model." (PMID 29593739, 2018). "STAT-6 deficient mice infected with ECTV-WT were better protected through generation of more effective NK cell and IFN-γ responses that allowed the otherwise susceptible animals to overcome infection." (PMID 25751266, 2015).